P3R3URF-PIK3R3 (P3R3URF-PIK3R3 readthrough)
Synonyms: LOC110117498-PIK3R3
Gene: Protein-coding gene on chromosome 1 (46,043,661 to 46,176,488, reverse strand). Ensembl gene ENSG00000278139.
Genetic constraint (gnomAD): Loss-of-function variants: 26 observed, 26.77 expected, observed/expected ratio (o/e) 0.97, 90% interval 0.71 to 1.35. The upper end of that interval is the gene's LOEUF score, 1.35, which puts it in group 5 of 6, group 1 being the genes least tolerant of losing a copy. Missense variants: 357 observed, 318.11 expected, observed/expected ratio (o/e) 1.12, 90% interval 1.03 to 1.23. Synonymous variants: 94 observed, 108.6 expected, observed/expected ratio (o/e) 0.87, 90% interval 0.73 to 1.03.